PCSK9 (proprotein convertase subtilisin/kexin type 9)
Diseases named in the same sentence as PCSK9 in open-access papers (continued):
Sharing a sentence is not in itself a finding about the gene and the disease.
atherosclerosis (continued). "In addition, preclinical studies also revealed that PCSK9 has pleiotropic effects other than plasma LDL-C regulation and could be a key molecule in the pathophysiology of atherosclerosis." (PMID 36982171, 2023). "However, although PCSK9-Il1a-/- animals show reduced IL-1β secretion, this does not appear to be the driving factor for atherosclerosis, because PCSK9-Il1b-/- animals do not show a reduction in plaque size." (PMID 37701434, 2023). "In addition to this classical pathway, recent research has also found that PCSK9 plays other roles in the development of atherosclerosis via non-classical mechanisms, such as inflammation, apoptosis and immune pathways." (PMID 38115042, 2023). "Moreover, there is a positive correlation between PCSK9 (proprotein convertase subtilisin/kexin type 9), a regulator of hepatocyte LDL receptor, and PTX3, confirming once again its clinical use in assessing atherosclerosis." (PMID 36553147, 2022). "Besides this last one and PCSK9 inhibitors, also IONIS-ANGPTL3-LRX (target: hepatic ANGPTL3 mRNA; NCT02709850) and AKCEA-APOCIII-LRX (target: hepatic APOC3 mRNA; NCT02709850) are in development in the atherosclerosis field." (PMID 36505351, 2022). "In prospective cohort studies, plasma PCSK9 level was correlated with enhanced atherosclerosis progression and elevated probability of future cardiovascular events independently of LDL plasma levels, suggesting alternative roles for PCSK9 in the pathogenesis of atherosclerosis." (PMID 36324757, 2022). "We detected attenuation of atherosclerosis in HFHC diet–fed mice with PCSK9-AAV–induced atherosclerosis following 18 weeks of semaglutide treatment, yet we were not able to detect regression of aortic atherosclerosis using a 6-week semaglutide treatment regimen." (PMID 34673572, 2021). "Interestingly, PCSK9 has been known to have various effects beyond LDL-C, which has been reported to be related to hypercoagulability and promote thrombosis to accelerate atherosclerosis." (PMID 34809656, 2021). "Our previous study showed that a nanoliposomal vaccine targeting PCSK9 could significantly induce the generation of antibodies inhibiting the plasma PCSK9 and thereby reducing the plasma LDL-C in an experimental model of atherosclerosis." (PMID 34504898, 2021). "PCSK9 induces endothelial cell apoptosis through the Bcl-2/Bax–Caspase9–Caspase3 mitochondrial pathway and the p38/JNK/MAPK signaling pathway to alter the integrity of the endothelium, ultimately promoting endothelial dysfunction and the development of atherosclerosis." (PMID 32169071, 2020). "Nevertheless, PCSK9 is mainly a modifier of atherosclerosis rather than a trigger itself." (PMID 33364976, 2020). "Here, we aimed to characterize the vascular effects of PCSK9 inhibition in APOE*3Leiden.cholesteryl ester transfer protein (CETP) mice, a mouse model for familial dysbetalipoproteinemia with human-like lipoprotein metabolism, on atherosclerosis development, inflammation and EPC and CAC number." (PMID 31366894, 2019). "Because the study subjects in Protocol I were all patients with atherosclerosis, ethically, we could not use policosanol alone to investigate its effect on PCSK9 in this population." (PMID 25478000, 2014). "In humans, PCSK9 levels significantly correlate with the classical parameters of metabolic syndrome such as obesity, serum insulin levels, fasting blood glucose, and hypertension, whose effects on atherosclerosis progression are also independent of LDL metabolism." (PMID 39940773, 2025).
atherosclerosis (continued). "However, there may still be lack of correlation between the plasma PCSK9 level and the severity of subclinical atherosclerosis in patients without symptoms of cardiovascular diseases." (PMID 36970356, 2023). "Regarding PCSK9, although this protein could potentially have effects on atherosclerosis that are independent of cholesterol levels, the direct mechanism of involvement is still unknown, driving a gap in the knowledge of such a predominant player in cardiovascular disease." (PMID 36361853, 2022). "Detection of reduced Glp1r expression in the livers of Glp1rTie2–/– mice prompted us to assess whether hepatic indices of metabolism or inflammation were differentially regulated in atherosclerosis-prone, PCSK9-AAV–treated, HFHC diet–fed mice treated with or without semaglutide." (PMID 34673572, 2021). "Notably, as many of these patients have severely diminished LDL-R function, hence traditional therapies that work through the LDL-R pathway like statins, ezetimibe and PCSK9 inhibitors may not achieve the magnitude of LDL-C lowering necessary to reduce atherosclerosis progression." (PMID 36382159, 2022). "Delaying the process of atherosclerosis neither cure CVD nor reduce disability, so the potential benefits of PCSK9 inhibitors are limited." (PMID 33935749, 2021). "A single intravenous injection of the PCSK9 mAb, alirocumab, in hyperlipidemic APOE*3Leiden.CETP transgenic mice, decreased non-HDL-C, inflammatory parameters, and atherosclerosis lesion size and improved plaque stability in a dose-dependent manner." (PMID 33440821, 2021). "Increasing data suggest that the effect of PCSK9 on LDL cholesterol and on atherosclerosis in particular is not limited solely to its effect on the LDL receptor." (PMID 33076542, 2020). "Although the investigations on the interaction of CRP with lipid indicating a connection between CRP and atherosclerosis have started from early on in the laboratory 12, no data have been provided yet to link CRP, PCSK9 and LDL uptake." (PMID 27633999, 2016). "Thus, mice lacking PCSK9 protein have low plasma LDL cholesterol levels and are protected from developing atherosclerosis." (PMID 38469142, 2024). "In our study, we employed the proprotein convertase subtilisin/kexin type 9 (PCSK9) gain-of-function (GOF) model in conjunction with a high-fat diet, which has been demonstrated to induce atherosclerosis and fatty liver in mice without the necessity of genetic modification." (PMID 39409049, 2024). "Interestingly, a reciprocal relationship between PCSK9, oxLDL and one of its receptors, LOX-1, has been proposed in the context of atherosclerosis in non-pregnant populations, contributing to the development of the disease." (PMID 35624732, 2022). "However, to date, the effect of pharmacological inhibition of PCSK9 and ANGPTL3 on regression of atherosclerosis has not been investigated." (PMID 31843957, 2020). "In line with these suggestions that PCSK9 exerts LDL-R-independent effects related to atherosclerosis, a triple knockout mouse with PCSK9−/−, LDL-R−/−, and ApoB−/− revealed less atherosclerosis than an LDL-R−/− and ApoB−/− double knockout mouse without any differences in cholesterol levels." (PMID 33364976, 2020). "However, the role of exercise on PCSK9, LOX-1 and VCAM-1 in atherosclerosis has not been reported." (PMID 32325897, 2020).
dyslipidemia (255 papers, 2010 to 2026). "The recent 2026 American College of Cardiology/American Heart Association dyslipidemia guideline emphasizes the clinical importance of targeting PCSK9, APOC3, Lp(a), and ANGPTL3." (PMID 42164756, 2026). "Despite these limitations, the study provides valuable real-world insights into long-term LDL-C control, treatment persistence, and clinical outcomes in high-risk dyslipidemia patients receiving PCSK9-mAb therapy." (PMID 40760109, 2026). "This reflects an absolute risk reduction of 9% and a relative risk reduction of 56%, underscoring the additive benefit of PCSK9 inhibitors for secondary prevention in high-risk diabetic patients with persistent dyslipidemia." (PMID 40688979, 2025). "Significant correlations between PCSK9, lipid profile parameters, and the Castelli and triglycerides-glucose indices suggest a potential role of PCSK9 as a biomarker of dyslipidemia and cardiometabolic risk." (PMID 41516208, 2025). "Together, these observations identify PCSK9 as a mechanistic link between systemic metabolic state and peripheral nerve integrity, and they highlight the need for targeted studies of PCSK9 in neuropathies associated with diabetes, obesity, and dyslipidemia." (PMID 41002444, 2025). "Although PCSK9 shows a positive relationship with body mass index and is considered to be associated with metabolic syndrome, the effects of PCSK9 on MASH and MAFLD are contradictory." (PMID 39963241, 2025). "Subsequently, in the following year, the relationship between dyslipidemia and PCSK9 mutations was discovered, drawing attention to a new trend in cholesterol-lowering drugs." (PMID 39176329, 2024). "The discovery of gain- or loss-of-function mutations in PCSK9 in patients with dyslipidemia led to the development of PCSK9 inhibitors with unprecedented lipid-lowering properties." (PMID 39149582, 2024). "In patients with T1D, an elevated plasma concentration of PCSK9 is associated with components of metabolic syndrome, poor glycemic control and high EAT volume." (PMID 38532033, 2024). "The PCSK9 concentration is associated with metabolic syndrome parameters, poor glycemic control and increased EAT volume in patients with T1D." (PMID 38532033, 2024). "In our cohort, we also found an association between increased levels of PCSK9 and the presence of dyslipidemia and hyperTG." (PMID 38532033, 2024). "Larger longitudinal studies are needed to examine the role of PCSK9 in the development of metabolic syndrome in high-risk neonates born to overweight, obese, or diabetic mothers." (PMID 38440108, 2024). "Using meta-regression modeling, we quantified the association between 15 individual MACE components and dyslipidemia biomarkers, based on 54 clinical trials of statins and PCSK9 inhibitors, which amounted to 270,471 subjects in total." (PMID 38304061, 2023). "PCSK9 seems to be closely associated with the progression of atherothrombosis, leading to cardiovascular disease, especially in dyslipidemia." (PMID 37892538, 2023). "This connection between dyslipidemia, inflammation, and atherosclerosis is further supported by a number of studies demonstrating that PCSK9 inhibition lowered LDL levels and CAD risk." (PMID 38054817, 2023). "Dyslipidemia has been linked to genetic mutations of lipid-regulating genes, such as proprotein convertase subtilisin/kexin type 9 (PCSK9)." (PMID 38054817, 2023). "A multinational prospective study involving 539 CAD patients indicated that plasma PCSK9 levels were associated with metabolic syndrome, insulin resistance, and obesity." (PMID 38049831, 2023). "Despite the previously observed close associations of PCSK9 with dyslipidemia, it was reported that PCSK9 also have effects on other metabolic diseases, but the results were controversial." (PMID 35498417, 2022). "Despite chronic HBV infection often being associated with dyslipidemia, the number of studies analyzing PCSK9 in HBV-infected patients is still limited." (PMID 35162992, 2022).
dyslipidemia (continued). "In a univariate analysis, smoking, overweight, atherogenic dyslipidemia, and PCSK9 levels were associated with future risks of cardiovascular events." (PMID 34270402, 2021). "In CKD, increased plasma lipid levels are associated with elevated levels of PCSK9, suggesting a role for PCSK9 in CKD-associated dyslipidemia." (PMID 34680522, 2021). "This study aimed to investigate the association between PCSK9, dyslipidemia, and future risk of cardiovascular events in a population of black Africans." (PMID 34270402, 2021). "Reduced lipoprotein lipase activity but increased low-density lipoprotein (LDL) production and pro-protein convertase subtilisin/kexin type 9 (PCSK9) expression have been associated with CKD-related dyslipidemia." (PMID 34442464, 2021). "The levels of PCSK9, smoking, overweight, and atherogenic dyslipidemia were associated with future risks for cardiovascular events in univariate analysis." (PMID 34270402, 2021). "The aim of the study was to analyze the clinical and diagnostic value of serum PCSK9 concentrations and their connections with disease severity, inflammation, metabolic syndrome, and impact of systemic therapies in psoriatic patients." (PMID 32225075, 2020). "G carriers of PCSK9 rs562556 had a lower risk of dyslipidemia including decreased serum LDL concentrations in meta-analysis without separating ethnicities." (PMID 32727492, 2020). "What’s more, a growing number of studies have explored the association of PCSK9 with cardiovascular metabolic disorders beyond dyslipidemia." (PMID 33023603, 2020). "In 2019, Jeedundang investigated in a clinical manner PCSK9 levels and their association with metabolic parameters in 436 subjects in terms of the view of metabolic syndrome and menopausal processes." (PMID 32456228, 2020). "Participants with PCSK9 LOF variants were less likely to have dyslipidemia when compared with other participants (26.2% vs 54.3%, P < .001) and had lower total cholesterol levels (mean values 161 vs 194 mg/dL, P < .001)." (PMID 30726226, 2019). "Considering the co-existence of HCC and metabolic syndromes which are often associated with the persistent nutritional overload, altered PCSK9 regulation is indeed a possibility." (PMID 30386595, 2018). "After adjusting for changes in TC levels, numbers of circulating EPCs, and history of metabolic syndrome, use of cilostazol remained independently associated with changes in the plasma PCSK9 levels [beta = 0.20 (95% confidence interval = 0.02-0.48), P = 0.04]." (PMID 29296222, 2017). "According to the current study, a history of metabolic syndrome and changes in TC levels and EPCs count are independently associated with changes in plasma PCSK9 concentrations." (PMID 29296222, 2017). "Plasma levels of PCSK9, apoC3, and sdLDL-C were associated with the current dyslipidemias classification (all p<0.001)." (PMID 27713142, 2017). "After adjusting for changes in levels of TC and numbers of circulating EPCs and history of metabolic syndrome, use of cilostazol remained independently associated with changes in plasma PCSK9 levels." (PMID 29296222, 2017). "Dyslipidemia commonly present in patients with chronic kidney disease (CKD) has been recently linked to increased proprotein convertase subtilisin/kexin type 9 (PCSK9) serum concentration." (PMID 26481479, 2016). "This study highlights four key findings regarding the real-world use of PCSK9-mAb therapy in high-risk dyslipidemia patients: First, treatment persistence was high, with over 90% of patients remaining on PCSK9-mAb therapy since treatment initiation over a 3-year period." (PMID 40760109, 2026). "Additionally, the lack of publication bias further strengthens the robustness of our conclusions, such that PCSK9 inhibitors play an important role in the management of dyslipidemia and cardiovascular risk." (PMID 40110272, 2025).
dyslipidemia (continued). "Given the inherently elevated baseline cardiovascular risk in patients with T2DM, combined with the challenge of residual dyslipidemia despite maximal statin therapy, there is a compelling need to rigorously evaluate the clinical benefits of PCSK9 inhibitors in this specific high-risk subgroup." (PMID 40688979, 2025). "As research continues to unravel the full potential of PCSK9 inhibitors, their role in reducing cardiovascular risk is likely to be further refined, ultimately enhancing long-term outcomes and the overall well-being of patients with dyslipidemia and CVD." (PMID 39650150, 2024). "Current guidelines for the management of dyslipidemia recommend the use of PCSK9 inhibitors in patients at high or very high risk of future cardiovascular events, in whom LDL-C targets are not achieved with maximally tolerated statins and ezetimibe, and in those who are statin intolerant." (PMID 39539858, 2024). "Moreover, proprotein convertase subtilisin/kexin type 9 (PCSK9), a serine protease produced by the liver, has been shown to be involved in the development of dyslipidemia and CVDs caused by AS." (PMID 38994197, 2024). "Statins and PCSK9 inhibitors have shown promise in managing dyslipidemia associated with MASLD." (PMID 39000046, 2024). "In conclusion, the current study shows that while both HFD and PCSK9-GOF cause dyslipidemia, leading to renal fibrosis, the underlying mechanisms might differ." (PMID 39094771, 2024). "Notably, according to our findings, a high intake of saturated fatty acids and trans fatty acid from butter appears to substantially elevate the risk of dyslipidemia, platelet reactivity, and increased levels of PCSK9." (PMID 37892538, 2023). "In addition to evidence that dyslipidemia increases risk of Alzheimer’s disease, there are several recent reports demonstrating a link between PCSK9 and Alzheimer’s disease pathogenesis." (PMID 35404972, 2022). "Besides, the mechanisms whereby thyroid-stimulating hormones modulate the serum levels of PCSK9 and the risk of dyslipidemia in patients with hypothyroidism should also be further investigated." (PMID 34784265, 2022). "Moreover, different polymorphisms of the PCSK9 gene influence circulating levels of molecules related to the lipid metabolism that lead to a risk for dyslipidemias and cardiovascular diseases." (PMID 33925815, 2021). "Similarly, in our population, the prevalence of metabolic syndrome, although previously associated with PCSK9, is comparable between sexes and does not influence the sex-specific relationship between PCSK9 and memory." (PMID 33776743, 2021). "However, the underlying effect of PCSK9 on HHcy-accelerated dyslipidemia of macrophages is still uncertain." (PMID 34660746, 2021). "The study has shown that circulating PCSK9 level is increased in postmenopausal women with metabolic syndrome and suggested that this elevation might exacerbate the risk of MetS amongst those women." (PMID 32456228, 2020). "In fact, at least in this population, diabetes, obesity and the metabolic syndrome seem to override the influence of PCSK9 on LDL metabolism, as demonstrated by the loss of the correlation between PCSK9 and LDL cholesterol in patients with altered metabolic phenotype." (PMID 31672148, 2019).